CRYBG1 (crystallin beta-gamma domain containing 1)
Description:
May function as suppressor of malignant melanoma. It may exert its effects through interactions with the cytoskeleton.
Synonyms: AIM1; ST4
Tractability: PROTAC: ubiquitination databases record sites on it.
Gene: Protein-coding gene on chromosome 6 (106,360,717 to 106,572,017, forward strand). Ensembl gene ENSG00000112297.
Subcellular location (Human Protein Atlas): Cytosol; Microtubules; Nucleoplasm
Genetic constraint (gnomAD): Loss-of-function variants: 125 observed, 169.42 expected, observed/expected ratio (o/e) 0.74, 90% interval 0.64 to 0.86. The upper end of that interval is the gene's LOEUF score, 0.86, which puts it in group 3 of 6, group 1 being the genes least tolerant of losing a copy. Missense variants: 2,487 observed, 2,619.8 expected, observed/expected ratio (o/e) 0.95, 90% interval 0.92 to 0.98. Synonymous variants: 983 observed, 1,005.4 expected, observed/expected ratio (o/e) 0.98, 90% interval 0.93 to 1.03.
Homologues: Orthologues: chimpanzee CRYBG1 (99% identical), macaque CRYBG1 (95% identical), pig CRYBG1 (78% identical), mouse Crybg1 (73% identical), rat Crybg1 (72% identical), dog CRYBG1 (68% identical), rabbit CRYBG1 (62% identical), tropical clawed frog crybg1 (38% identical), zebrafish crybg1a (24% identical), zebrafish crybg1b (22% identical). Paralogues in human: CRYBG3 (20% identical), CRYBG2 (18% identical), CRYBB2 (4% identical), CRYBB1 (4% identical), CRYBA1 (3% identical), CRYBB3 (3% identical), CRYBA4 (3% identical), CRYGB (3% identical), CRYBA2 (3% identical), CRYGA (3% identical), CRYGS (3% identical), CRYGC (3% identical), and 2 more.
Diseases named in the same sentence as CRYBG1 in open-access papers:
CRYBG1 is named in the same sentence as 7 diseases in open-access papers, as found by Europe PMC text mining. Sharing a sentence is not in itself a finding about the gene and the disease. The quoted sentences say what the papers report.
melanoma (3 papers, 2024). A malignant, usually aggressive tumor composed of atypical, neoplastic melanocytes. "CRYBG1 (suppression of tumorigenicity 4) is a protein involved in cytoskeletal remodeling with potential roles in suppressing melanoma that was downregulated in both nuclear and cytoplasmic cell fractions." (PMID 39268460, 2024). "Initially, CRYBG1 was mainly localized to the putative chromosome 6 oncogene region of human melanoma and served as a good candidate suppressor because of its high expression level in suppressing melanoma cells." (PMID 39845946, 2024). "CRYBG1 (alias AIM1, absent in melanoma), located on Chr.6q21, was initially identified as a frequent target of LOH and tumor suppressor in melanoma." (PMID 38391914, 2024).
cholesteatoma (1 paper, 2022). A pathologic process characterized by the proliferation of keratinizing squamous epithelium resulting in the accumulation of keratin and cells in the middle ear and/or mastoid. "However, in our own middle ear expression dataset from the same patients, all 12 genes were DEGs for cholesteatoma: RTN4, RAB5A, CRYBG1, RGS22, HEPHL1, and SPTLC3 were upregulated, while APBB1IP, BHLHE41, ARID3A, C5AR1, CPT1B, and FAM227A were downregulated." (PMID 36699445, 2022).
prostate carcinoma (1 paper, 2024). A carcinoma that arises from epithelial cells of the prostate gland. "With the development of high-throughput technologies, CRYBG1 has been shown to be highly expressed in prostate cancer tissues." (PMID 39845946, 2024).
cancer (3 papers, 2024 to 2025). A tumor composed of atypical neoplastic, often pleomorphic cells that invade other tissues. "Focal CNAs often harbor cancer driver genes, supporting a possible oncogenic role of the identified CRYBG1 fusion transcripts." (PMID 38391914, 2024). "Although the role of CRYBG1 in different cancers is controversial, it is capable of interacting with the cytoskeleton." (PMID 39845946, 2024). "CRYBG1, an actin-binding protein implicated in cancer progression but with no reported role in LECs, emerged as a candidate." (PMID 40589731, 2025). "Furthermore, fusion transcripts involving oncogenes have been shown to exhibit increased expression in cancer, and we observed indeed strong expression of CRYBG1, FGFR2, and RTN4IP1 in MFM-223." (PMID 38391914, 2024). "CRYBG1 (AIM1) is a common marker and therapeutic target in cancer." (PMID 39845946, 2024).
CRYBG1 also shares sentences with these, for which no sentence is quoted: infection (1 paper); otitis media (1); tumor (1).